TNF (tumor necrosis factor)
Diseases named in the same sentence as TNF in open-access papers (continued):
Sharing a sentence is not in itself a finding about the gene and the disease.
melanoma (continued). "Tumor-promoting M2 macrophages can contribute to tolerance to MAPK inhibition, and their accumulation within tumors during treatment strongly correlates with an aggressive phenotype in different melanoma models, through different mechanisms, including VEGF and TNF-alpha secretion." (PMID 31730502, 2019). "The interaction between highly constitutive expression of MHC class II molecules at the surface of melanoma cells and LAG-3 greatly expressed on melanoma-specific CD4+ T cells elicits a local TNF-rich inflammatory environment, reducing the cytotoxic CD8+ T cell responses." (PMID 32039024, 2019). "Given the impact of TNFα and IFNγ on IL32 expression in melanoma cell lines, we investigated the expression of IL32 in the chemokine-rich melanoma tumor microenvironment using RNA sequencing data from tumor biopsies as part of The Cancer Genome Atlas (TCGA) dataset." (PMID 30953519, 2019). "The benefits of TNF blockade were further documented using the B16-Ova mouse melanoma model, reinforcing our own observations, and further justifying our ongoing TICIMEL clinical trial in advanced melanoma patients." (PMID 31417576, 2019). "Rb9 did not modify the melanoma lysate response in relation to IL-12, TNF, and IL-10 secretion but significantly reduced IL-6." (PMID 32010152, 2019). "While Th9 cells mediated a higher inhibition on melanoma tumor growth than PBS control, the addition of TNF-α during Th9 cell differentiation further improved their antitumor efficacy, demonstrating that TNF-α improves the antitumor efficacy of Th9 cells." (PMID 30717817, 2019). "In contrast, serum TNF-α levels in the melanoma-bearing mice (M) were not significantly different from levels seen in control animals (C)." (PMID 29588627, 2018). "Moreover, TNF-α, Interleukin-6 (IL-6), and TGF-β are related to epithelial-to-mesenchymal transition (EMT) in multiple cancers such as melanoma and breast cancer." (PMID 30139382, 2018). "Similarly, T-cell cytokines, TNF-α and IFN-γ, synergized with oncogene inhibition with a BRAFV600E inhibitor, vemurafenib, to induce cell cycle arrest in melanoma." (PMID 29796172, 2018). "Our study suggests that zymosan-induced upregulation of TLR-2, TLR-4 and TNF-α gene expression and of TNF-α release; together with increased level of lymphocyte proliferation may play a role in the inhibition of melanoma progression." (PMID 29588627, 2018). "In our previous study, increased expression of IFN β after intratumoral GET of control plasmid gWiz Blank was observed in murine melanoma tumor in vivo, therefore we determined the expression of IFN β and TNF α after intratumoral GET of the three control plasmids examined in this current study." (PMID 29382170, 2018). "We found that the differential expression genes were enriched in JAK-STAT, FOXO, TNF and cell cycle signaling pathways and particularly the cell cycle pathway, which is similar to the results of the non-BRAFi-resistant melanoma cell lines." (PMID 30400954, 2018). "In the B16 melanoma subcutaneous tumor model, CQ treatment consistently upregulated iNOS, while downregulating Arg1 in melanoma-infiltrating macrophages, concomitant with the increased expression of IFN-γ, IL-12p40, IL-12p35, and TNF-α, and downregulation of IL-10 in tumor tissues." (PMID 29491374, 2018). "Recent data have shown that upon melanoma cell lines, TNF and IL-1 showed no significant overall effect on expression of molecules involved in metastatic processes." (PMID 29318162, 2017). "Melanoma WM35 cell line was previously found to be resistant to TNF-α but not to TRAIL induced apoptosis." (PMID 28278159, 2017). "Two months after the first B16K1 melanoma cell inoculation, B16K1 melanoma cell re-injection in the surviving TNF- and TNFR1-deficient mice did not compromise overall survival, demonstrating that animals were totally vaccinated towards B16K1 melanoma cells." (PMID 29273790, 2017).
melanoma (continued). "Thus, along with our preclinical data, those observations on human melanoma suggest that TNF potently induces the expression of PD-L1, PD-L2 and TIM-3 in melanoma upon anti-PD-1 therapy." (PMID 29273790, 2017). "Also, we have shown aspirin can effectively inhibit TNF-α -induced upregulation of NF-kappaB and ICAM-1 expression during in vitro migration and invasion of human melanoma cells." (PMID 27270229, 2016). "Pxy00 where the T-cells and TNF-α are absent and both melanoma populations are present and where all populations are present." (PMID 27063839, 2016). "Additional studies might investigate IAP-independent predictors of response for SMAC-mimetics such as TNF-α, which has been shown to sensitize melanoma cells to LCL161, as differential levels of TNF-α have already been observed in GIST." (PMID 27167336, 2016). "In tumors, five genes (KIT, MGMT, MITF, TERT, and TNF) exhibited methylation levels significantly different between tumor groups including acral compared to nonacral melanomas and matched primary lesions and metastases." (PMID 26106605, 2015). "Other agents have been investigated in conjunction with melphalan, including tumor necrosis factor-alpha (TNF-α), interferon-gamma (IFN-γ), actinomycin D, and ADH-1, which is a cyclic pentapeptide, that inhibits N cadherin expression important in melanoma cell adhesion and migration." (PMID 26140669, 2015). "Finally, curcumin inhibits TNF-α-induced EMT, thereby suppressing the invasiveness and metastatic potential of melanoma cells." (PMID 26305550, 2015). "This supports that neither apoptosis nor necroptosis in RIPK3-expressing A375 and IGR melanoma cells is dependent on autocrine TNF signalling." (PMID 26355347, 2015). "Accordingly, TNFα induced cell death to a greater extent in the FKBP51-silenced melanoma cells, compared to non-silenced control melanoma cells." (PMID 26101251, 2015). "In conclusion, the present study has shown that macrophage IL-1β and TNF-α may promote VEGF-C expression in TAMs and may have a role in melanoma lymph node colonization." (PMID 25120672, 2014). "Recombinant tumor necrosis factor α (TNFα) is also licensed by several regulatory agencies worldwide (but not by the US FDA), for the treatment of limb-threatening soft tissue sarcoma and melanoma." (PMID 25537519, 2014). "In the present study, TNF-α and IL-1β were found to cooperate to promote the colonization of peritoneal lymph nodes by murine melanoma cells, when they were used at a non-toxic dose." (PMID 25120672, 2014). "We next analyzed whether Ipilimumab could also trigger ex-vivo NK cells to produce anti-tumor cytokines, such as TNF-α, during co-cultures with CTLA-4+ melanoma cells." (PMID 23634660, 2013). "Since both p38 MAPK and NFκB inhibitors partially decreased the secretion of TNFα from MM96L cells, crosstalk may exist between these and other pathways as the p38 MAPK pathway was shown to be upstream of the NFκB pathway in A2058 melanoma cells." (PMID 23965971, 2013). "From the present data, it may be suggested that Foxp3 participates in tumor growth and the modulation of the IL-2, IFN-γ and TNF-α cytokines and CD25, and that it may play a role in the immunosuppression of melanomas, possibly via this pathway." (PMID 24179494, 2013). "From these data, it may be suggested that Foxp3 participates in melanoma growth, the modulation of the IL-2, IFN-γ and TNF-α cytokines and CD25 expression, and that it also plays a possible role in immunosuppression." (PMID 24179494, 2013). "The new moiety called NGR-TNF was shown to transiently enhance tumor vessel permeability, thus increasing the penetration of chemotherapy agents in murine models of lymphoma, melanoma, and spontaneous prostate cancer without TNF-related systemic toxicity." (PMID 24062984, 2013). "The administration of the anti-TNF-α mAb did not alter the tumor growth in melanoma-bearing control mice." (PMID 23028986, 2012).
melanoma (continued). "Lipopolysaccharides can stimulate normal human melanocytes to produce IL-1β, TNFα, IL-6, IL-8, CCL2, CCl3, and CCL5, and chemotherapy of melanoma-bearing mice results in enhanced expression of CCL5 and the CXCR3 ligands CXCL9, CXCL10, and CXCl11 by tumor cells." (PMID 22745913, 2012). "Significant benefits for melanoma patients have been obtained through targeted modification of tumour vasculature, immunity and inflammation, such as IFN-α and isolated limb perfusion of high-dose TNF-α therapies." (PMID 22415295, 2012). "Both the resident Vδ1+ and the migrated Vδ2+ T cells may contribute to control tumor growth, as suggested by their ability to produce cytokines with proven anti-tumor activity (TNF-α and IFN-γ) and to kill melanoma cell targets in vitro." (PMID 23189169, 2012). "Accordingly, we also found that splenocytes isolated from melanoma-bearing mice treated with Cl-IB-MECA released increased amounts of TNF-α compared with splenocytes from control animals (data not shown)." (PMID 23028986, 2012). "When living B16 melanoma cells were transduced with IL-2 or TNF and injected into mice, no tumor growth occurred as a result of CTL and NK becoming activated by those released cytokines." (PMID 22899945, 2012). "Mice that rejected the IL-2- or TNF-transduced B16 melanoma cells showed no lasting recall memory, even though an immune response rejected the initial IL-2- or TNF-transduced tumor cells." (PMID 22899945, 2012). "Finally, there was a dramatic increase of TNF-α and IL-6 following co-culture of CTL with DC and lysates from H-1PV-infected melanoma cells." (PMID 22029859, 2011). "Previous reports showed that early apoptotic melanoma cells or pure apobodies failed to induce mDCs, and either TNF-α, Poly I:C or cytokine cocktails were necessary to achieve DCs maturation and Ag presentation." (PMID 17448240, 2007). "Unfortunately, the examination of the TNF autovaccine in established tumours in the B16F10 melanoma model was not possible because of two reasons." (PMID 15026813, 2004). "A prolonged duration of response was found in melanoma patients: 14 months after IHP with TNF-αvs 6 months after IHP without TNF-α." (PMID 12610519, 2003). "There were no changes in the morphology of the melanoma cells (control and TNF-α stimulated) at 8 or 24 h." (PMID 12966436, 2003). "To elucidate the cellular mechanism, we used a Fas-ligand (Fas-L) specific ribozyme (Fas-Lribozyme) to suppress the expression of Fas-L but not Fas or TNF-α in B16F10 melanoma cells." (PMID 12177809, 2002). "Our findings align with those of prior studies suggesting that TILs in melanoma, although morphologically brisk, may be functionally compromised when key cytokines such as TNF-α and IFN-γ are absent at the protein level." (PMID 41150769, 2025). "Tumor Necrosis Factor-α (TNFα), which may facilitate EMT induction via the NF-ҡB signaling pathway stimulation, leads to the expression of the proinflammatory cytokine interleukin 6 (IL6) gene, which, in turn, activates autophagy in melanoma cells." (PMID 38398197, 2024). "In addition, TNF, through its binding to TNFR2, induced Tregs proliferation in B16F10 mice with metastatic melanomas, resulting in the escape of tumor cells from immune surveillance, and Treg cell depletion in TNFR2-deficient animals reduced the number of metastases of CM." (PMID 38474115, 2024). "To evaluate the contribution of the glycosphingolipid pathway to the TNF-induced melanoma cell dedifferentiation process, we monitored the impact of eliglustat, an inhibitor of glucosylceramide synthase (GCS), by RT-qPCR on various markers of melanoma dedifferentiation." (PMID 39136013, 2024). "Indeed, de-differentiation of melanoma cells towards NCSC states (which have low MITF activity) is one mechanism in which melanoma cells escape T-cell detection and respond to inflammation, such as TNFα." (PMID 39092608, 2024).
melanoma (continued). "To investigate cellular death in the B16F10 mouse melanoma cell model and its correlation with the mechanism of RIPK1 downregulation rather than kinase inhibition, we employed various tool molecules, including LD4172, T2I, TNFα, Smac mimetic LCL161, and the pan-caspase inhibitor Z-VAD-FMK." (PMID 39681571, 2024). "To date, several studies sought to assess the risk of melanoma and non-melanoma skin cancer (NMSC) in patients treated with biologics and found that TNF-α inhibitors may increase this risk." (PMID 38276003, 2023). "The expression of LL-37 on myeloid cells in dermis is correlated with levels of proinflammatory cytokines such as IL-23p19, IL-17A, and TNF-α, which could promote tumor progression via angiogenesis in melanoma and non-melanoma skin cancers." (PMID 36980564, 2023). "Together, our findings are consistent with the hypothesis that melanoma growth in the skin does not trigger KC-dependent mechanisms of LC activation, but rather that melanoma-derived TNF-α may induce LC migration once large primary tumors have developed." (PMID 37043573, 2023). "In this case, we would expect there to exist conditions under which melanoma cells can maintain TNF-α production through autocrine signaling, or not, depending on whether the feedback loop is engaged." (PMID 37043573, 2023). "While previous studies have shown an increased risk of melanoma and non-melanoma skin cancer (NMSC) in patients receiving TNF-α inhibitors, the risks associated with newer biologics (IL-12/23 inhibitors, IL-23 inhibitors, IL-17 inhibitors) and Janus kinase (JAK) inhibitors remain less known." (PMID 38276003, 2023). "Importantly, JAK1/2 inhibition with Ruxolitinib selectively suppresses the growth of IFNγR1KO but not scrambled control melanomas, depending on T cells and host TNF." (PMID 36008408, 2022). "Additionally, they demonstrated that melanoma cells were able to reduce IFNγ secretion by this subset while TNFα was not affected, which is in contrast with the TNFα up-regulation we observed." (PMID 35173725, 2022). "In the syngeneic B16 melanoma cell line transfer system, B cell depletion by anti-CD20 antibody treatment resulted in a two-fold bigger tumor volume and impaired interferon-γ (IFN- γ) and tumor necrosis factor (TNF-α) production from CD4+ T cells and CD8+ T cells." (PMID 36033455, 2022). "Surprisingly, IFNγR1KO melanomas harbor an aberrantly active mTOR-JAK1/2 axis, which, when targeted with an FDA-approved JAK1/2 inhibitor Ruxo, results in potent and selective suppression of IFNγR1KO but not scrambled control melanomas, in a T cell and host TNF-dependent fashion." (PMID 36008408, 2022). "Furthermore, more broad investigations into the phenotype and function of TGF-β or IL-10-producing regulatory and IFN-γ- or TNF-α-expressing inflammatory B cells in human melanoma are still lacking." (PMID 35909944, 2022). "B vitamins affect the increased level of TNF-α and IL-6 in the tumor microenvironment, the activation of NF-κB factor in macrophages and the increased abundance of Bacteroides, Faecalibacterium and Prevotella, which stimulate the response to immunotherapy in NSCLC and melanoma patients." (PMID 36428677, 2022). "Finally, ex vivo treatment with nPKC-θi2 increased the expression of TNF-α and IFN-γ in CD8+ T cells from responder and resistant patients with advanced melanoma, consistent with our previous work showing that PKC-θ inhibition regulates the expression of these cytokines in human memory CD4+ T cells." (PMID 35326747, 2022). "It is worth noting, however, that our dedifferentiated melanoma cells did not revert to their melanocytic state in the absence of TNFα, and this may reflect a temporal switch to an irreversible dedifferentiation state, that is driven by epigenetic changes." (PMID 34073253, 2021).
melanoma (continued). "In order to study the direct effects of TNFα on tumor cell biology, we engineered cells of two different origins continually overexpressing human TNFα gene: epithelial colorectal adenocarcinoma lines HT29, HCT116, and malignant melanoma lines A375 and M4Beu of neural crest origin." (PMID 33957885, 2021). "In particular, the TWEAK-induced activation of the non-canonical NF-κB signaling pathway, which induces production of TNF-alpha and sensitizes tumor cells to death, may play a protective role in thick non-metastasizing melanomas." (PMID 34638912, 2021). "When CTLA-4 and PD-1 are co-blocked in B16 melanoma cells vaccinated with B16-Flt3-ligand (Fvax), these agents synergistically increase the ratio of Teff to Treg and myeloid-derived suppressor cells, as well as the production of T cells that secrete IFN-γ and TNF-alpha." (PMID 31968651, 2020). "Mechanistically, T cell-driven inflammatory stimuli such as TNF-α, engage the transcription factor c-jun in tumor cells, which in turn reduces MITF levels, and consequently decreases the expression of melanocyte differentiation genes, thereby leading to melanoma cell dedifferentiation." (PMID 33276788, 2020). "More importantly, TNFα failed to activate BRAF in PPP2R2A-depleted melanoma cells." (PMID 31015455, 2019). "More specifically, in C57BL/6 mice inoculated with B16F-10 melanoma cells, capillary formation was prevented after exposure to AITC and PITC (25 μg/dose/animal/day), an effect which was mediated by reduction in the expression levels of NO and TNF-α, both of which promote capillary formation." (PMID 31003534, 2019). "This correlates with a significant upregulation of TNFα expression in the tumor microenvironment, conferring antiapoptotic protection and resistance to MAPK pathway inhibitors through the combined action of TNFα and MITK (melanocytic specific transcription factor), in the case of melanoma cells." (PMID 31652660, 2019). "Furthermore, activated T-cell exosomes carrying bioactive FasL, a member of the tumor necrosis factor (TNF) family, may enhance the metastasis of melanoma and lung cancer cells by increasing the expression of MMP9." (PMID 30925925, 2019). "In fact, it is known that the local production of pro-inflammatory cytokines such as MIF and TNF in the tumor microenvironment of solid tumors such as GBM and melanoma induce the production of NO and other immunosuppressive mediators that may favor growth and invasiveness of GBM." (PMID 30441775, 2018). "There are also data suggesting an increased risk of melanoma in patients on anti-TNF treatment for IBD, with a 1.5−2× increased risk compared to those not exposed, however this is also impacted by an increased risk of melanoma associated with IBD independent of the use of biologic therapy." (PMID 30065229, 2018). "In addition, copper-mediated oxidation of the cysteine residues in the cross-linking of S100A4 prometastatic activity in tumor microenvironment results in an increase in NF-κB activation and TNF-α secretion in human melanoma cells, particularly in RAGE-transfected melanoma cells." (PMID 29069865, 2017). "Thus, synergism of TNF/TNFR1 deficiency and anti-PD-1 is likely not restricted to melanoma but applies to other cancers, such as lung carcinoma, which can benefit from anti-PD-1 according to phase 2 and phase 3 clinical trials." (PMID 29273790, 2017). "Moreover, GP-B1, the acidic polysaccharide obtained from GpM, not only significantly inhibited the growth of cancer cells, but also improved cellular immune response with increased levels of TNF-α, IFN-γ, IL-10 and IL-12 in the serum of melanoma-B16-bearing mice." (PMID 27708693, 2016). "Importantly, our mRNA-based microarray and NanoString screens revealed that frequently used normalization genes are not stably expressed in melanoma cells exposed to melanoma-specific CTLs or their cytokines (IFNγ/TNFα)." (PMID 27625650, 2016).